STAT3 (signal transducer and activator of transcription 3)
Diseases named in the same sentence as STAT3 in open-access papers (continued):
Sharing a sentence is not in itself a finding about the gene and the disease.
tumor (continued). "As exosomal miR-204-3p is known to promote tube formation in vascular endothelial cells via the ATXN1/STAT3 pathway, TAK-981, a SUMOylation inhibitor, can inhibit miR-204-3p sorting into exosomes and inhibits tumor growth and angiogenesis." (PMID 37391814, 2023). "Three signaling pathways (STAT3/VEGFA, HIF1/VEGFA, and AKT) have been reported to regulate tumor angiogenesis." (PMID 36720310, 2023). "STAT3 is a downstream effector of c-MET/EGFR and is activated in CSCs and primarily expressed in the invasive tumor margin." (PMID 37924112, 2023). "It was found that naringenin can not only activate the caspase-9/caspase-3/PARP/C-PARP apoptosis pathway but also inhibit tumor cell proliferation and growth via the inhibition of JAK-2/STAT-3." (PMID 37298981, 2023). "In another report, in a mouse ovarian tumor model, metformin suppressed STAT3 and c-Myc through activation of FOXO3 tumor suppressor protein in the tumor and subsequently downregulates PD-L1 expression, which leads to activation of CD8+ TILs." (PMID 37686159, 2023). "Intravenous injection of LDLs promoted tumor growth in the xenograft nude mice, and also increased p-JAK2, p-STAT3, and Ki-67 expression, and downregulated caspase-3 expression." (PMID 37900720, 2023). "In protumor conditions, Th2, Tregs, Th17, and myeloid-derived suppressor cells (MDSCs) secrete IL-1, IL-10, IL-17, and TGF-β through STAT3 and STAT5 signaling, which precludes immune function in the tumor microenvironment (TME)." (PMID 38094755, 2023). "Activation of STAT3 can regulate angiogenesis and metastasis by the upregulation of VEGF, which is a crucial regulatory gene in angiogenesis, tumor growth, and metastasis." (PMID 37749554, 2023). "In a previous study of our group, we identified raloxifene to exert an inhibitory effect on IL-6/gp130/STAT3 signaling in PDAC cells and on tumor growth in a xenograft mouse model." (PMID 36495330, 2023). "In the tumor samples, CD47 and p-STAT3 expression levels were much higher in the KRASMUT patients than in the KRASWT patients." (PMID 36413402, 2023). "Fusobacterium simultaneously triggers the IL-6/p-STAT3/c-MYC signaling pathway and encourages M2-type differentiation of macrophages through a TLR4-dependent mechanism, promoting tumor growth." (PMID 36845103, 2023). "BCSC interacting with macrophages initiates their tumor-promoting function, and these TAM produce high levels of IL6, which in turn initiates activation of the STAT3 signaling pathway and consequent enrichment of BCSC." (PMID 37445860, 2023). "The modified EVs delivered the signal transducers and activators of transcription 3 (STAT3) siRNA for GBM treatment, which significantly inhibited the growth of orthotopic U87MG xenografts and enhanced the median survival time of the tumor-bearing nude mice." (PMID 37717008, 2023). "Our results suggest that cinobufagin can inhibit the STAT3 signaling pathway in NSCLC, thereby inducing cell apoptosis and suppressing cell proliferation, migration, and tumor growth (in an NSCLC xenograft model)." (PMID 37928418, 2023). "Previous findings have shown that tumor cells increase PD-L1 expression through transcription factors such as IRF1/4, c-Myc, EGR1, c-Jun, HIF-1α, NF-κB, ATF3 and STAT3." (PMID 36854755, 2023). "The transcriptional activity of STAT3 is broadly associated with cancer pathology, and dysfunction in the FAK/STAT3 axis induced by EBA treatment resulted in the impairment of BCSC survival, angiogenesis and tumor propagation." (PMID 37185776, 2023). "Activation of NF‐κB, STAT3 and ERK signalling pathways were also highly induced in tumour tissues of Peli3 WT mouse compared to those in KO mouse." (PMID 37341064, 2023). "IL-8 induces the activation of JAK/STAT3 oncogenic signaling cascade that supports CRC cell proliferation, tumor angiogenesis, and metastasis." (PMID 37760840, 2023).
tumor (continued). "Metformin mediates dual blocking of STAT3-PDL-1 and c-Myc-PDL1 pathways in tumor through upregulation of FOXO3, and therefore, it enhances CD8+ TILs activation." (PMID 37686159, 2023). "The signal transducer and activator of transcription 3 (STAT3) protein is constitutively active in several forms of human malignancies and is essential for tumor development, including GBM." (PMID 37744256, 2023). "Inhibiting VEGFR2/STAT3/HIF‐1α axis signaling pathway can inhibit the proliferation, migration, and tumor angiogenesis of hucCT‐1 and RBE cells." (PMID 37329188, 2023). "Signaling by G-CSF, GM-CSF, and tumor-derived cytokines via STAT5 and STAT3 induces the development of lipid transporters and improves the absorption of lipids that are available in high amounts in the tumor microenvironment (TME)." (PMID 37735675, 2023). "Among them, STAT3 and STAT5 are often considered pro-tumor, while STAT1 is generally considered the key downstream effector of IFN-γ, capable binding GAS and inducing ISG transcriptions." (PMID 37275859, 2023). "SC-78, a derivative of regorafenib, also inhibits tumor growth and metastasis in TNBC by interfering with the paracrine and autocrine pathways of VEGF-A through the SHP-1/STAT3 signaling axis." (PMID 38203502, 2023). "Signaling pathways downstream Gas6/AXL signaling, including PI3K/AKT/mTOR, NF-κB, JAK/STAT3 and RAS/RAF/MEK/ERK, play critical roles in tumor cell cycle regulation, malignancy and drug resistance." (PMID 37265798, 2023). "Zhang and colleagues have described the formation of HMW oligomerized protein complexes, particularly impacting p62 (a protein involved in autophagy) and the transcription factor STAT3, as a VPF tumor-selective proteotoxic mechanism." (PMID 36882436, 2023). "Further GSEA analysis of tumor hallmarks indicated that oncogenic pathways, including IL6/JAK/STAT3 signaling, KRAS signaling, and Wnt/β‐catenin signaling pathway were engaged in the high‐risk group." (PMID 37334893, 2023). "The Janus kinase 2/signal transducer and activator of transcription 3 (JAK2/STAT3) pathway is involved in different biological processes, such as immunity, cell division, cell death, and tumor formation." (PMID 37686148, 2023). "The tumor-promoting effects of IL-17 and its receptor IL-17R are achieved through direct influence on tumor cells via the IL-6/JAK2/STAT3-related pathway." (PMID 37762066, 2023). "As a result, HSSP-BMSCExo effectively crossed the BBB, silenced STAT3, restored GBM sensitivity to TMZ, and eventually inhibited tumor proliferation in a TMZ-resistant U251 (U251-TR) brain tumor mouse model." (PMID 37144620, 2023). "Increased secretion of LIF in turn activates the STAT3 signaling pathway and, therefore, WP1066 was able to suppress tumor growth and greatly improve mouse survival." (PMID 37190167, 2023). "Classical therapeutic targets of tumours involved in PTBP1 include HER2, STAT3 etc., and inhibitors against these targets have been developed." (PMID 36635500, 2023). "All of them usually activate MAPK, PI3K/AKT, STAT3, NF-κB, Ras, TGF-β and β-catenin signaling pathways for the development of tumor diseases." (PMID 37393391, 2023). "The IL-6/STAT3 signaling pathway can effectively trigger EMT and increase the number of tumor stem cells." (PMID 37857728, 2023). "AMG 510 treatment for 8 days significantly suppressed tumor growth, inhibited KRAS activity, STAT3 phosphorylation, and CD47 expression, and stimulated miR-34a expression in tumor tissues." (PMID 36413402, 2023). "IL-6 has been shown to activate signaling pathways leading to tumor proliferation, the most studied of which are the JAK and STAT3 pathways." (PMID 37047012, 2023). "A study by Panni has shown that M-MDSCs play a significant role in promoting tumor stemness and EMT by regulating the STAT3 pathway through the secretion of IL-6, and MDSCs also induce angiogenesis in a STAT3-dependent manner." (PMID 37857728, 2023).
tumor (continued). "Tumor-secreted IL-1 induces Leukemia inhibitory factor (LIF) expression and downstream JAK/STAT3 activation, generating inflammatory CAFs." (PMID 38124183, 2023). "In response to the development of BRCA, many important signaling pathways have been identified to maintain tumor stemness, such as NOTCH, Wnt/β-catenin, STAT3, hedgehog, and other signaling pathways." (PMID 36835637, 2023). "Expression of these pathways can be further amplified in a STAT1-dependent manner via co-depletion of FAK and STAT3, resulting in extensive infiltration of tumour-reactive CD8 T-cells and further restraint of tumour growth." (PMID 36977556, 2023). "IFN-λ acts in conjunction with related genes such as STAT1, STAT2, and STAT3 to affect the JAK-STAT signaling pathway, which promotes tumor progression." (PMID 37697300, 2023). "On the whole, it was illustrated that higher the expression of STAT1, STAT2, STAT3, STAT4, STAT5A, and STAT5B, the lower the tumor purity." (PMID 36968603, 2023). "After inoculation of 10 × 103 ALL cells, 2.5 × 106 STAT3–/– T cells were enough to prevent tumor growth in all (9/9) recipients, while all (9/9) recipients given TCD-BM alone had progressive tumor growth and died by 15 days after HCT." (PMID 37526084, 2023). "IL‐6 activates the signal transducer and transcriptional activator 3 (STAT3) through the JAK/STAT pathway, which, in turn, encourages inflammatory responses and the development of tumours." (PMID 38041544, 2023). "Based on published data demonstrating that the IL-6/STAT3 axis accelerates EMT and leads to further tumor progression." (PMID 36814597, 2023). "In addition, A-FABP expression in CD11b+F4/80+MHCII-Ly6C- phenotype TAMs facilitates protumor IL-6/STAT3 signaling by regulating the NFkB/miR-29b pathway, and A-FABP deficiency significantly decreases the growth and spread of breast tumors in transgenic and syngeneic tumor models." (PMID 36880535, 2023). "Simultaneously, STAT3/Foxp3 axis potentially enforced the Tregs function in TME of EC and served as a promising target for the anti‐tumor immunotherapy." (PMID 36226375, 2023). "SHP-1 expression has an inverse relationship with DNMT1 and STAT3; its expression decreases when the activation of DNMT1 and STAT3 in tumor cells increases." (PMID 38203502, 2023). "Opening of the PTP domain by a conformational change in SHP-1 increases enzymatic activity and contributes to a tumor control phenotype by inhibiting the activation of the Janus kinase/signal transducer and activator of transcription (JAK/STAT3) pathway." (PMID 38203502, 2023). "However, the pharmacologic or genetic inhibition of STAT3 increases IL-6 expression in GBM cells and GSCs through unclear mechanisms, suggesting that therapeutically muting STAT3-dependent IL-6 induction may inadvertently suppress the tumor immune response to GBM." (PMID 37242454, 2023). "We revealed that CMTR1 synergistically controlled tumor cell proliferation and antitumor immunity by binding to the TSS of STAT3." (PMID 37024465, 2023). "Depleting fibroblastic STAT3 or CCL2, or murine CCR2 attenuated the FAP-induced MDSC infiltration and tumor-promoting effects in vivo." (PMID 36708970, 2023). "It has been suggested that tumor growth and angiogenesis can be reduced by eliminating lactate-induced M2 macrophage polarization by inhibiting ERK/STAT3 signaling." (PMID 37781517, 2023). "For mechanism of STK24 action, it was evident that STK24 prevents STAT3 from polyubiquitin–proteasomal–mediated degradation and STK24 regulated tumor angiogenesis through STAT3/VEGFA signaling pathway." (PMID 36720310, 2023). "TROP2 influences tumor cell proliferation, migration, invasion, and metastasis by modulating the downstream signaling pathways MAPK (ERK1/2), JAK2/STAT3, and PI3K." (PMID 37457288, 2023).
tumor (continued). "Taken together, these data suggested that KRAS signaling can suppress miR-34a expression via the PI3K/STAT3 axis, which in turn relieves miR-34a–dependent repression of CD47, leading to escape from innate immune surveillance and tumor progression." (PMID 36413402, 2023). "Tumor stromal cells enhanced the cell invasion and the cell signaling activities of both PI3K/Akt and JAK/STAT3 pathways in patient PTC-derived CSCs." (PMID 36982542, 2023). "Canonical pathways that were significantly enriched included fibrosis signaling, the tumor microenvironment pathway, estrogen receptor signaling, TREM1 signaling, ID1 signaling, STAT3 signaling, and HIF1 signaling." (PMID 38028629, 2023). "Moreover, in desmoplasia‐associated cancers, fibroblast activation protein (FAP) could up‐regulate the expression of CCL2 through STAT3 signalling pathway, which enhances the recruitment of myeloid‐derived suppressor cells and promotes proliferation of tumour matrix and leads to poor prognosis." (PMID 36872292, 2023). "IL-6 also activates human CD14+ peripheral blood nuclear cells through the STAT3 pathway producing CCL18 and TGFβ, which leads to the induction of the EMT with tumor-promoting effects." (PMID 37190141, 2023). "The phosphorylation of the key transcription factor STAT3, serving as a target of the IL‐6 receptor beta (glycoprotein 130, gp130) or TFEB in macrophages, mediated M2 polarization and promoted tumor cell proliferation and migration." (PMID 36794651, 2023). "Western blotting results confirmed that vortioxetine hydrobromide reduced the levels of p-STAT3 Y705, c-Myc, Bcl-2 and Mcl-1 in PDX tumor xenografts." (PMID 37147297, 2023). "The results showed that bigelovin significantly inhibited tumor growth and inhibited liver/lung metastasis, possibly by interfering with the IL6/STAT3 and cofilin pathways." (PMID 38111074, 2023). "Studies have shown that S100A8 expression is positively correlated with PD-L1 levels in tumor samples and can induce PD-L1 in macrophages by activating PI3K/Akt, MAPKs, NF-κB, and STAT3 to increase PD-L1 transcription." (PMID 37701037, 2023). "The gene pathway association between these overexpressed hypoxia genes would be via the PVT1/PRC2/STAT3 pathway and the ERK/HIF-1α/p70S6K cascade, which signals tumour-induced angiogenesis." (PMID 37048688, 2023). "Activation of different signaling cascades such as JAK2/STAT3, NF-κB, PI3K/AKT/mTOR, and Wnt/β-catenin pathways through the tumor microenvironment leads to upregulation of antiapoptotic proteins." (PMID 36986514, 2023). "Specifically, IL‐6 can induce NF‐κB in GBM, resulting in the activation of signal transducer and activator of transcription 3 (STAT3) and increased tumor aggressiveness." (PMID 36627748, 2023). "In the hypoxic tumor microenvironment, epthelial autophagy activates the AMPK/ULK1 and JaK2/STAT3 pathways and sustains mitochondrial metabolism to nourish cells and promote cell proliferation." (PMID 38273841, 2023). "Interaction of BCSC with macrophages initiates their tumor-promoting function, and these TAM produce high levels of IL6 which in turn initiates activation of the STAT3 signaling pathway and consequent enrichment of BCSC." (PMID 37445860, 2023). "HNSCC tumor cells produce IL-6, CXCL8, and EGF, which improve the survival and angiogenic potential of endothelial cells through the activation of the STAT3/AKT/ERK signaling pathways." (PMID 38003931, 2023). "After migrating to the tumor microenvironment, M-MDSCs activate the CD45 tyrosine phosphatase, which selectively inhibit the activity of STAT3." (PMID 36923251, 2023). "Overexpression of UBE2S promotes tumor cell proliferation and migration by regulating the VHL/HIF-1α/STAT3 signaling pathway." (PMID 38115063, 2023). "Once IL-6 binds to its receptor on the plasma membrane of tumor or stroma cells, the pathway JAK1/STAT3 is activated and controls genes involved in proliferation, survival, invasion and metastasis formation." (PMID 36639824, 2023).
tumor (continued). "The cleavage of the crosslinking, activated by PDT-ROS production, is critical for PDG escape from the MOF surface and deeper penetration into the tumor lesion, resulting in the suppression of MDSC formation via the STAT3 pathway." (PMID 36987269, 2023). "Signal transducer and activator of transcription 3 (STAT3) signalling serves an important role in carcinogenesis and cellular senescence, and its inhibition in tumour cells represents an attractive therapeutic target." (PMID 36825563, 2023). "Abnormal activation of STAT3 also leads to abnormal overexpression of various proteins, including Mcl-1, Bcl-2, Bcl-xl, survivin, Cyclin D1, c-Myc, and VEGF, which leads to tumor development." (PMID 36911202, 2023). "The immunosuppressive effect of MDSC is inhibited by the STAT5 or STAT3 signaling reduction, or the genetic removal of the fatty acid translocase CD36, resulting in improved CD8+ T cell performance and slower tumor development." (PMID 37735675, 2023). "The tumor samples were used to evaluate the expression of HIF-1α, Nrf2, HO-1, cMyc, cyclin D1, mTOR, and STAT3." (PMID 37465088, 2023). "The authors concluded that both STAT3 and pSTAT3 are upregulated in OvCa compared to normal, and that expression was correlated with FIGO stage, tumor grade, and poorer prognosis regarding both OS and PFS." (PMID 37173951, 2023). "Two leucine residues of the PCBP1 protein bind to STAT3 5′UTR and, by reducing the amount of oncogenic protein STAT3, serve as a tumor suppressor." (PMID 36769304, 2023). "IL-6 activates the corresponding receptor IL-6R on tumour cells and CAFs by means of autocrine–paracrine, which leads to differential activation of the STAT3 and MEK/ERK signalling pathways, resulting in tumour development." (PMID 37927475, 2023). "Mechanismly, the suppressed STAT3 signaling pathway mediated nuciferine-inhibited OSCC cell functions and tumor growth." (PMID 37833979, 2023). "IL‐6 upgrades miR‐25‐3p through STAT3/c‐MYC signaling to downgrade PTPRO in HCC monocytes, ascending PD‐L1 expression and tumor growth in vivo." (PMID 38098217, 2023). "IL-6 binds with IL-6R to induce the activation of STAT3 and activated STAT3 binds to the promoter region of the VEGF gene to increase transcription, promoting the tumor angiogenesis." (PMID 37892997, 2023). "Taken together, Res inhibited STAT3 signaling through modulation of PIAS3, SHP1, SHP2, and SOCS3, thereby attenuating tumor growth and increasing sensitivity to TMZ." (PMID 37298405, 2023). "Nonetheless, it highlights BRG1 and the molecular pathways it regulates, particularly the STAT3 pathway, as important factors to understand in GBM tumour aggressiveness." (PMID 37433987, 2023). "Further analysis of only the microdissected tumor cells metastatic to lymph nodes (n = 6) showed higher levels of stress and immune signaling proteins (GCN2, Lck Tyr505, Rb, Rb Ser780, and Stat3 Tyr727)." (PMID 37491309, 2023). "In pathological conditions similar to tumor progression, such as skin fibrosis, FAK is a major effector molecule that is activated downstream of the STAT3 pathway, and it has been shown to correlate with activation of the ERK-CCL2 signaling pathway." (PMID 38313431, 2023). "A key transcription factor often upregulated in OvCa, STAT3, and other STAT proteins contributes to the protumorigenic functions and drives the TME towards a tumor supporting niche." (PMID 37173951, 2023). "Therefore, regulating the JAK/STAT3 signaling axis may be an effective target in tumor therapy." (PMID 38203502, 2023). "Venturing beyond these, other pivotal pathways like STAT3, NF-κB, and PI3K are instrumental in shaping TAM activities, steering them toward either tumor promotion or suppression." (PMID 38035068, 2023). "In the analysis of Western Blot(WB) of tumor tissue,VCAM1,p-STAT3 and PD-L1 in NII.clusterB-PNI were up-regulate than that in other subtypes.In addition,we successfully constructed VCAM1 shRNA cell models of the GC cell lines SNU-216,NCC-24,HGC-27,SNU-1." (PMID 37563649, 2023).